MIR621 (microRNA 621)
Synonyms: hsa-mir-621; MIRN621
Gene: MicroRNA gene on chromosome 13 (40,810,766 to 40,810,861, forward strand). Ensembl gene ENSG00000207652.
Gene Ontology:
Biological process: miRNA-mediated post-transcriptional gene silencing
Cellular component: RISC complex